C14orf119 (chromosome 14 open reading frame 119)
Synonyms: FLJ20671
Tractability: PROTAC: ubiquitination databases record sites on it.
Gene: Protein-coding gene on chromosome 14 (23,094,692 to 23,100,456, forward strand). Ensembl gene ENSG00000179933.
Subcellular location: Mitochondrion
Subcellular location (Human Protein Atlas): Mitochondria; Cytosol
Gene Ontology:
Molecular function: protein binding
Cellular component: mitochondrion
Genetic constraint (gnomAD): Loss-of-function variants: 17 observed, 14.34 expected, observed/expected ratio (o/e) 1.19, 90% interval 0.81 to 1.74. The upper end of that interval is the gene's LOEUF score, 1.74, which puts it in group 6 of 6, group 1 being the genes least tolerant of losing a copy. Missense variants: 162 observed, 173.97 expected, observed/expected ratio (o/e) 0.93, 90% interval 0.82 to 1.06. Synonymous variants: 61 observed, 65.88 expected, observed/expected ratio (o/e) 0.93, 90% interval 0.75 to 1.15.
Homologues: Orthologues: pig C14orf119 (90% identical), rabbit C14orf119 (89% identical), guinea pig C14orf119 (85% identical), mouse 1700123O20Rik (84% identical), rat C15h14orf119 (84% identical), rat C16h14orf119 (71% identical), zebrafish C2H14orf119 (49% identical), tropical clawed frog c1h14orf119 (48% identical), Drosophila melanogaster CG12948 (21% identical).
Diseases named in the same sentence as C14orf119 in open-access papers:
C14orf119 is named in the same sentence as 3 diseases in open-access papers, as found by Europe PMC text mining. Sharing a sentence is not in itself a finding about the gene and the disease.
C14orf119 shares sentences with these, for which no sentence is quoted: Cranial meningocele (1 paper); partial epilepsy (1); trigonocephaly (1).